IL6 (interleukin 6)
Diseases named in the same sentence as IL6 in open-access papers (continued):
Sharing a sentence is not in itself a finding about the gene and the disease.
tumor (continued). "PEA or AM11095 inhibited the secretion of IL-6 and IL-8, reduced the activation of the NF-kB pathway, decreased the expression of VEGF and Placental growth factor (PLGF) in TNBCs, and inhibited tumor cell migration in vitro." (PMID 36564457, 2022). "At 72 h, colon and tumour tissue were collected and examined for histopathological changes and RT-PCR for genes of interest; TLR4, MD-2, CD-14, MyD88, IL-6, IL-6R, CXCL2, CXCR1, and CXCR2." (PMID 35962138, 2022). "The results obtained by our group show that MCPIP1 downregulation in ccRCC induces the secretion of IL6 and IL8, which stimulates the development of the tumor vasculature." (PMID 36138026, 2022). "SASP factors such as IL-6, IL-8, GROα, and IGFBP-7 participate in an autocrine feedback loop to reinforce growth arrest in senescent cells for tumor suppression." (PMID 35379822, 2022). "In vivo experiments showed that FAVO significantly delayed the growth of SGC-7901 tumor-bearing nude mice and induced higher serum IL-2 and IFN-γ and reduced serum IL-6." (PMID 35392643, 2022). "In contrast, a TEC subpopulation expressing CXCL2, IL-6 and ACKR3 was markedly suppressed in tumor with only marginal increase after chemotherapy." (PMID 36253784, 2022). "While this treatment had minimal direct effect on cancer cells, it led to a reduction of serum levels of IL-6 and EGF, known CAF secreted factors and reduced tumour growth was mediated by a reduction of CXCL12 and destruction of ECM." (PMID 35479076, 2022). "Inflammation-related mediators released by tumor cells inhibit T helper 1 (Th1) cells, e.g., IL-2, Interferon-gamma (INF-γ) and TNF-α, and induce Th2 peripheral cytokines, e.g., IL-10, IL-6 and IL-4." (PMID 35057010, 2022). "Among these DEGs, 5 genes were down-regulated in tumor group including IL1B, AIM2, IL6, NLRP3, and NLRP6." (PMID 36127654, 2022). "It produces a series of chemokines and cytokines that regulate immunity, including IFN-γ, TNF, IL-6, and CCL5, which have the function of regulating immune response and anti-tumor and are related to the improvement of the overall survival rate of patients." (PMID 36686745, 2022). "And IL-33 can stimulate the production of cytokines (IL-4, IL-6) and chemokines (CCL2, CCL3, CCL7, CXCL1), which are also involved in the construction of the tumor microenvironment." (PMID 36110250, 2022). "While CD4+ memory resting T cells contribute most T-cells within the tumour microenvironment (TME), their presence is highly influenced by CCL2, ANG, CHI3L1, IL-6 and IL-8." (PMID 36430641, 2022). "Many proinflammatory cytokines, including IL-6, IL-8, IL-1, and TNF-, have been identified as altering bone tumor angiogenesis, progression, and tumor microenvironment." (PMID 36013319, 2022). "In turn, activated adipocytes secrete chemokines (CCL2, and CCL5), cytokines (IL-1β, IL-6, TNF-α), and angiogenic factors (VEGF), all required for the promotion of tumor growth, angiogenesis and metastasis." (PMID 35493456, 2022). "Inflammation affects cytokine receptor-mediated signaling pathways that mediate CRC tumor progression, including the TNF, IL-1, IL-6, and NF-κB pathways." (PMID 36291619, 2022). "Previous studies have demonstrated that IL6-mediated dysregulation of JAK/STAT3 pathway significantly correlates with proliferation, metastasis and survival of tumor cells." (PMID 36032140, 2022). "In BC cells, exosome IL-6 promotes tumor development, exosome HSP70 promotes tumor progression in cells of MSC, and exosome TGF- promotes tumor growth in cells of LAMA84." (PMID 35813829, 2022). "IL-6-Nab combined with HMA completely eradicated OCSCs, and this combination blocked IL-6/IL6-R/pSTAT3-mediated ALDH1A1 expression, providing a strategy for tumor recurrence after chemotherapy." (PMID 36387165, 2022).
tumor (continued). "It was concluded that a reduction in serum levels of TGF-β, IL-6, and IL-17 indicated the potential suppressive effects of radiation therapy and chemotherapy on Th17 cells and TGF-β-producing tumor cells in the early stages of BC patients." (PMID 35248028, 2022). "To model the real tumor microenvironment of PDAC patients, we established a PDX model and performed treatment with a neutralizing antibody against IL6 or in vivo-optimized si-circCUL2." (PMID 35189958, 2022). "M2 macrophages secrete many factors, such as, IL-6, IL-8, IL-10, TGF-β, PGE2 and MMP7, and these macrophages promote immunosuppression and tumor growth." (PMID 36059695, 2022). "Inflammatory cells produce tumor necrosis factor α, transforming growth factor β, interleukin-6, and other cytokines, and these inflammatory agents regulate nuclear factor (NF)-κβ and the STAT3 pathway and encourage metastasis in tumor cells." (PMID 35387666, 2022). "The inflammatory cytokine IL-6 secreted by TAMs induces EMT and promotes tumor cell invasion in lung cancer via the COX-2/PGE2/β-catenin signaling pathway." (PMID 36679900, 2022). "In a variety of cancers, IL-6/JAK/STAT3 is overactivated, which promotes tumor cell proliferation, survival, invasiveness and metastasis and inhibits the antitumor immune response, which is related to the poor prognosis of tumors." (PMID 35359408, 2022). "Previous studies have shown that IL-6 can activate STAT-3, the major downstream signaling pathway for IL-6, and it plays a role in the maintenance of CRC cell survival and tumor initiation." (PMID 36466926, 2022). "We found that inhibiting interleukin-6/leukemia inhibitory factor (IL6/LIF) cytokine signaling activates estrogen signaling and blocking both pathways was synergistic in inhibiting tumor cell growth." (PMID 36230597, 2022). "It is seen that transforming growth factor-beta (TGF-β) acts via IL-6 to activate the signal transducer and activator of transcription-3 (STAT-3) in the tumor cells, which requires the soluble IL-6 receptor present in the tumor cells." (PMID 36059323, 2022). "It facilitates the polarization of TAMs to M2 phenotype, which can release IL6 and CXCL8 to increase the expression of TNF in CRC cells, leading to the activation of NFKB1 pathway and then promotes tumor angiogenesis and metastasis." (PMID 35186730, 2022). "In breast cancer, palmitoylated proteins in tumor EVs can act as TLR2 ligands leading to upregulation of proinflammatory cytokines and chemokines including CCL2, IL-6 and GCSF in macrophages." (PMID 35320943, 2022). "Stimulation of the IL-6 / JAK / STAT3 pathway in cancer cells modulates the expression of several genes involved in the proliferation, survival and transformation of tumor cells." (PMID 35948877, 2022). "A pDC population marked by high expression of LAG3 has been identified in tumor-invaded lymph nodes and skin metastasis featured by a limited secretory IFN-α ability and enhanced IL-6 production." (PMID 36230990, 2022). "In combination with chemotherapy or through administration locally at the tumor site, Nr-CWS prolongs the survival of patients with advanced cancers and increase the levels of cytokines, such as IL-1, IL-6, TNF-α and IFN, in tumor tissue." (PMID 36110249, 2022). "TGF-β triggers interleukin (IL)-6 and vascular endothelial growth factor (VEGF) secretion in BM stromal cells (BMSCs), to increase paracrine IL-6 and VEGF-related tumor growth." (PMID 36578789, 2022). "The findings of CAF associated markers in response to exosomal telomerase at the first part of the study, especially the secretion of IL-6, fits well with the putative activation of TLR in inducing this cytokines secretion to promote tumor growth." (PMID 36180493, 2022). "The second class of signals consists of cytokines and chemokines such as IL-4, IL-6, IL-1, and CXCL1, that are mostly produced by the tumor stroma, which induce the suppressive activity of MDSCs via NF-κB, STAT1, and STAT6." (PMID 35890239, 2022).
tumor (continued). "Tumor resection eliminated TIM, but as tumors regrow, TIM express IL-6 again at the same level as in the primary implanted tumor." (PMID 35884700, 2022). "The components in the TME can directly secrete metabolites (such as IL-6, FGF-2, PDGF, MMPs, CXC12, VEGF, FGF, IL8/CXCL8, and PDGF-C) that induce tumor metastasis and tumor cell proliferation." (PMID 35571530, 2022). "In addition, polarized M2 macrophages produce IL-6 to promote the phosphorylation of the threonine 243 of phosphoglycerate kinase 1 (PGK1T243) mediated by 3-phosphoinositide-dependent protein kinase 1 (PDPK1) in tumor cells, promoting glycolysis and tumor progression." (PMID 35062950, 2022). "The two most important cytokines, IL-6 and IL-8 (CXCL8/IL-8), are involved in various spectrum cellular pathways responsible for the proliferation, metastasis, or tumor cell survival." (PMID 35986321, 2022). "IL-6 and TNFα pathways suggest a strict connection between inflammation mediators, which may stimulate pre-malignant cell proliferation, angiogenesis, and metastasis, and, tumor cells, which reversely stimulate other cells to produce pro-inflammatory and pro-angiogenic factors." (PMID 35335997, 2022). "IL-6 activates its receptor and the JAK2/STAT3 pathway, which can lead—in the tumor cells—to increased proliferation, survival and epithelial-mesenchymal transition." (PMID 35804810, 2022). "M1 macrophages (CD86+ and CD80+) release pro-inflammatory cytokines (e.g., IL-6, IL-12, TNF-α) to play an anti-tumor role, while M2 macrophages (CD206+) release pro-tumor cytokines (e.g., IL-4, IL-10, IL-13) to promote tumor progression and metastasis." (PMID 35432300, 2022). "All of these studies, in conjunction, highlight the potential of circulating cytokine levels as a clue to the status of the tumor immune microenvironment and the clinical outcome of ICI treatment, especially for IL-6 and INF-gamma levels." (PMID 35681606, 2022). "Given these preclinical observations, our findings regarding the correlation between IL-6 levels and [18F]FMISO-PET imaging-assessed tumor hypoxia seem biologically plausible." (PMID 34773163, 2022). "Many osteoclast-activating factors (IL-6, IL-1β, HGF and TNF-α) are released by the mutual interactions of tumour and bone marrow cells with a major involvement of RANKL, the decoy receptor OPG, and MIP-1α a." (PMID 36362718, 2022). "Moreover, increased features of NF activation noted in 4T1 tumor-bearing mice, which were the most visible in the 100 IU+cal group, may also be an effect of the increased tumor tissue concentration of IL-6, a cytokine that may activate fibroblasts through the induction of STAT3 phosphorylation." (PMID 36230508, 2022). "Among them, the activation of the STAT3 signaling pathway by IL-6 increases the number of CRC initiating cells, which can induce non-tumor stem cells to express stem cell markers and increase tumorigenic capacity in vivo." (PMID 35953863, 2022). "A recent follow-up study examined circulating tumor DNA (ctDNA) and nine soluble inflammatory biomarkers (CRP, IL-6, IL1RA, IL-18, Leptin, TNFα, adiponectin, fibrinogen, and PAI1) in blood samples from CANTOS patients." (PMID 36074553, 2022). "Research revealed that in the interaction between macrophages and lung cancer cells, IL-6 promotes the translocation of β-catenin from the cytoplasm to the nucleus via the COX-2/PGE2 pathway, which induces EMT and promotes tumor cell invasion." (PMID 35965509, 2022). "RAGE-depleted tumor exhibited lower expression of pro-inflammatory cytokines, and RAGE-depleted TAMs expressed significantly lower levels of IL-6 and VEGF-A." (PMID 36686729, 2022). "IL-6 and downstream activation of JAK2/STAT3 signaling play critical roles in tumor progression, establishment of a stem-like phenotype, and drug resistance." (PMID 35729402, 2022).
tumor (continued). "Th17 cells highly produce pro-inflammatory molecules, such as IL17, IL1β, IL6, IL23, and nitric oxide (NO), and promote tumor progression directly, and also indirectly via inducing angiogenesis." (PMID 36211375, 2022). "Both IL-6 and TNF-α, which have dual roles in immune response to tumor, were also elevated with the combination treatment." (PMID 36551577, 2022). "CAFs assist tumor growth and dissemination through the production of factors such as EGF, IL-6, TGF-β, and VEGF, which promote tumor cell proliferation and angiogenesis." (PMID 36010693, 2022). "Together, these findings emphasize the importance of IL-6 and STAT3 in multiple tumor-suppressive functions of TRAF3." (PMID 36291813, 2022). "Through the secretion of soluble substances such as IL6 and PGE2, tumor cells directly stimulate the M2 polarization of macrophages." (PMID 35890239, 2022). "Tumor-derived PCs seem to upregulate PD-L1 expression, a negative regulator of anti-tumor T cell responses, and overexpress the PC marker RGS5, which, together with IL-6, modulates the expression of the adhesion molecule ICAM-1 and promotes T-cell anergy." (PMID 36012149, 2022). "Regarding the mechanism of BTC progression, IL-6 was reported to activate the JAK–STAT3 pathway, which promotes tumour cell proliferation and invasion." (PMID 35948981, 2022). "It is mainly induced by tumor-microenvironment factors, such as TGF-beta 1 and IL-6, which activate the increased expression of the EMT-transcription factor (TF) Slug." (PMID 35219646, 2022). "Upon histopathological analysis, along with histopathological classification and staging, the degree of CD4, CD8, and CD163 cell infiltrations and expressions of interleukin-6 and matrix-metalloproteinase-11 (MMP-11) in the primary tumor were assessed." (PMID 36010928, 2022). "In contrast with the saline group, the level of IL-6, IFN-γ, and TNF-α in the V+E@Gel group were enhanced by 2-, 1.6-, and 4-fold, respectively, demonstrating the strong and robust immune reaction in tumor tissues." (PMID 36145556, 2022). "IL‐6 targeting along with anti‐CTLA‐4 therapy has been found to reduce M2 cells and PD‐1+ CD8+ T cells and further improved the survival of tumor‐bearing mice." (PMID 35301813, 2022). "From this scenario of cell reprogramming conducted by EVs, cytokines such as IL-6 can induce phosphorylation events of transcriptional factors such as STAT3, contributing to tumor growth and metastasis of breast cancer." (PMID 35386696, 2022). "The plasma concentrations of IL-6, IL-10, and TNF-α were significantly increased in the serum of tumour-bearing SID animals compared to the healthy controls." (PMID 36010845, 2022). "Several tumor-related markers, including the KRAS signaling pathway, IL-6/JAK/STAT3 signaling pathway, and inflammatory response were identified, which were enriched in low-risk patients." (PMID 36244998, 2022). "TEX significantly induced the accumulation of MDSCs expressing cyclo-oxygen-ase 2 (Cox2), IL-6, VEGF, and Arg1 and promoted tumor progression via the PGE2 and TGF-β molecules in TEX." (PMID 35163380, 2022). "Zoledronic acid is a potential therapy to change tumor microenvironment, affecting the secretion of CCL5 and IL-6." (PMID 35875135, 2022). "The combined use of anti-interleukin-6 and anti-CTLA-4 was found to promote antitumour activity via enhancement of T-cell tumour infiltration." (PMID 35626020, 2022). "IL-4, IL-6 and IL-10 are abundantly expressed in TME and play more pro-tumor role, while IL-2, IL-12, IL-15 and IL-18, which are immunomodulatory or pro-inflammatory factors, are restricted in the TME and play more anti-tumor role." (PMID 36698392, 2022).
tumor (continued). "The mRNAs of JUN, IL-6 and PPARG were reduced in tumor cells and up-regulated by Chidamide treatment." (PMID 36425653, 2022). "Through the secretion of pro-inflammatory cytokines such as IL-6, IL-1β, and TNF-α, macrophages can contribute to tumor-promoting inflammation." (PMID 35565306, 2022). "Myeloid cells within the tumor microenvironment produce inflammatory mediators such as IL-6 and TNF-a, promoting tumor growth, inflammation, and angiogenesis." (PMID 36230500, 2022). "Recently, a phase I clinical trial of DNX-2401 treating patients with recurrent GBM suggested increased numbers of macrophages and proinflammatory factors, including IL-6 and TNF-α, in posttreatment tumor specimens." (PMID 36013403, 2022). "Based on a gene expression microarray and a protein array analyses, IL-1, IL-6, IL-8, and CXCL1 were chosen as candidates responsible for tumor-induced osteoclastogenesis." (PMID 36614130, 2022). "IL-6/JAK/STAT3 signaling is able to drive the proliferation, survival, invasiveness, and metastasis of tumor cells, leading to a poor clinical prognosis in many types of cancers." (PMID 35734424, 2022). "In the tumor immune microenvironment, the IL6-JAK-STAT3 pathway is hyperactivated in a multitude of cancers, which suppresses the anti-tumor immune response and promotes tumor progression." (PMID 36105094, 2022). "In CRC, TAMs showed pro-inflammatory properties and expressed cytokines such as IFNγ, IL6 and IL1, which activated type-1 polarised CD4+- T cells (Th1) cells mediating an anti-tumour immune response." (PMID 36497148, 2022). "In human glioma cells, bidirectional cross-talk between tumor cells and neutrophils via the Fas (APO-1, CD95)/FasL pathway increased cellular viability and stimulated neutrophil cytokine production (IL-6, IL-8)." (PMID 35269652, 2022). "The secretion of TNF-α, IFN-γ, IL-6, and other cytokines by CD4+ T cells can change the TME, induce the local invasion of T lymphocytes into the tumor, inhibit the synthesis of DNA and RNA of tumor cells, and thus, induce the apoptosis of tumor cells." (PMID 36389763, 2022). "LPS can also regulate TLR4 to induce IL-6 response through MAPK and PI3K pathways, which promote tumor progression." (PMID 34141706, 2021). "IL-6 and IL-8 are proinflammatory cytokines released from HNSCC, with possible roles in tumor migration, angiogenesis, and immunity." (PMID 34063134, 2021). "We reported that TIN mice showed a significantly decrease in IL-6 and TGF-β, increase in the expression of epithelial markers (E-cadherin), and decrease in the expression of mesenchymal markers (N-cadherin) in tumor microenvironment." (PMID 34064322, 2021). "We found that combination of α-IL-6 and α-CTLA-4 further inhibited tumor growth compared to IgG control groups and other single treatments." (PMID 34093869, 2021). "Growth factors and cytokines, such as TGF-β, MIF, IL-6, and SDF-1, which are produced in the TME and are important in the recruitment of MSCs to TME, further augment tumor growth and metastasis by promoting the neovascularization of the tumor." (PMID 34681692, 2021). "Inducing a cascade of signaling molecules, i.e., pro-tumorigenic cytokines interleukin-6 (IL-6), IL-8 and tumor necrosis factor-α (TNF-α), induces the NF-κB transcriptional survival program, protecting tumor cells against cell death." (PMID 34439134, 2021). "Supporting the finding that JAK2/STAT3 suppresses STING in tumor cells, co-administration of IL-6, a JAK2/STAT3 activator, impaired the anti-tumor effects of cGAMP." (PMID 33790360, 2021). "Dietary supplementation of creatine in tumor-bearing Wistar rats prevents muscle atrophy via alleviating inflammation and proteolysis as evidenced by reduced inflammation factor (TNF-α and IL-6) and muscle atrophy gene (MAFbx and MuRF1)." (PMID 34199575, 2021).